CD80 (CD80 molecule)
Diseases named in the same sentence as CD80 in open-access papers (continued):
Sharing a sentence is not in itself a finding about the gene and the disease.
leukemia (30 papers, 2008 to 2025). A malignant (clonal) hematologic disorder, involving hematopoietic stem cells and characterized by the presence of primitive or atypical myeloid or lymphoid cells in the bone marrow and the blood. "We used lentiviral vectors encoding CD80 and CD86 to successfully transduced the L1210 leukemia cells, and the expression of CD80 and CD86 was remarkably upregulated in leukemia cells." (PMID 36466863, 2022). "To upregulate the expression of costimulatory molecules on leukemia cells, we constructed a lentiviral vector encoding the CD80 and CD86 genes." (PMID 36466863, 2022). "In this study, CD80 and CD86 were overexpressed in L1210 leukemia cells through transduction of lentiviruses encoding CD80 and CD86." (PMID 32578140, 2020). "Indeed, tumor cells in 3 of 4 dogs with “mixed lineage” leukemias were positive for multiple myeloid-associated antigens, including CD80, favoring an AML with aberrant, typically weak, lymphoid antigen expression." (PMID 39224452, 2024). "In this study, we upregulated the expression of CD80 and CD86 in LEXs through genetically modifying parental L1210 leukemia cells with lentiviruses encoding CD80 and CD86 genes and compared the morphology and typical exosomal proteins on modified LEXs to their unmodified counterpart." (PMID 36466863, 2022). "Other studies reported satisfactory anti-leukemia responses using leukemia cell-derived EVs engineered to express high levels of the co-stimulatory molecules CD80 and CD86, or low levels of PDL-1." (PMID 40508186, 2025). "Lentivirus-mediated transduction of L1210 leukemia cells produced exosomes (LEXs) enriched with CD80/CD86, which enhanced dendritic cell activation, promoted Th1 cytokine production, and induced leukemia-specific cytotoxic T lymphocyte responses." (PMID 41426784, 2025). "For example, leukemia cells were transfected with lentiviral vectors encoding B7 co-stimulatory molecules, and the exosomes (LEX-8086) obtained expressed high levels of CD80 and CD86." (PMID 38890722, 2024). "CD200Fc, which links the extracellular domain of CD200 with the murine IgG2a Fc region, effectively inhibits resistance to tumor growth in CD80-transfected EL4 or C1498 leukemia tumor cell allograft mice." (PMID 37894750, 2023). "Taken together, our data suggest that leukemia cells can be genetically modified to upregulate CD80 and CD86 expression in LEXs." (PMID 36466863, 2022). "The other strategy to generate a whole leukemia cell vaccine is to genetically modify leukemia cells to express costimulatory ligands such as CD80." (PMID 35074008, 2022). "Preclinical in vitro studies have demonstrated that CD80 transduction enhances the T-cell stimulatory capacity and the immunogenicity of leukemia cells." (PMID 35074008, 2022). "In this study, we collected LEXs derived from mouse leukemia L1210 cells transduced with a lentiviral vector encoding CD80 and CD86 and investigated the anti-leukemia immunity of LEX-CD8086-targeted CD4+ T cells in vitro and in vivo." (PMID 36466863, 2022). "We found that transduced leukemia cell-derived LEXs (LEX-CD80, LEX-CD86, LEX-CD8086) carried ectopic levels of CD80 and CD86." (PMID 32578140, 2020). "Of note, TRuC-T cells cleared tumor in a Nalm6 leukemia model, which is known for its low expression of co-stimulatory ligands CD80 and CD86." (PMID 31064990, 2019). "In the present study, Ara-C up-regulated CD80 expression on the CD19+ human leukemia cell-line Nalm-6." (PMID 26444983, 2015). "In the previous study, we found that Ara-C up-regulated CD80 expressed on CD19+ human leukemia cell-line Nalm-6 and some specimens of B-ALL patient-derived cells." (PMID 26444983, 2015). "DAC- induced CD80 expression is also observed in a number of human leukemia and lymphoma cell lines." (PMID 23671644, 2013). "Similarly, another study aimed to improve anti-leukemia immune responses using leukemia cell-derived EVs loaded onto DCs modified to express co-stimulatory molecules CD80 and CD86 (LEX-8086)." (PMID 39572459, 2024).
leukemia (continued). "Our data showed leukemia cells could be genetically modified to upregulate CD80 and CD86 expression in LEXs." (PMID 36466863, 2022). "In addition to this intrinsic feature, A20 leukemia cells barely express CD80 allowing PD-L1 to interact in trans with PD-1 expressed on immune cells." (PMID 35795681, 2022). "For instance, it has been reported that THP-1 cells and the CD34 + (KG-1) leukaemia cell line incubated with varying concentrations of rhGM-CSF and rhIL-4 for 5 days showed upregulated levels of CD11c, CD80 and CD86 and of the cell-surface receptors CD40, CD209 (DC-SIGN) but failed to express CD83." (PMID 34800147, 2022). "Therefore, we proved that stimulatory and inhibitory interactions between effector cells and lymphoblastic target cells guide T-cell function against leukemia through CD80/86–CD28/CTLA-4 as well as PD-1–PD-L interactions." (PMID 27708227, 2016). "Significantly however, we find that, upon repeated exposure to antigen and adoptive transfer to tumor-bearing mice, 19-28z-CAR transduced human T cells display enhanced expansion and greater in vivo anti-leukemia efficiency than CD19-targeted T cells that are costimulated through CD28/CD80." (PMID 26110267, 2015). "Mass cytometry further revealed that YW3-56 treatment simultaneously suppresses leukemia stemness (CD44/CD133 downregulation) and promotes myeloid differentiation (CD11b/CD14 upregulation), as well as enhances immunogenic activation (CD80/CD86 increase)." (PMID 41304891, 2025). "Subsequent studies have shown that leukemia cell vaccines co-expressing CD80 and GM-CSF can be used for immunotherapy of Ph+ ALL (acute lymphoblastic leukemia, ALL) patients, which can strongly inhibit the progression of leukemia." (PMID 39575257, 2024). "DBA/2 mice immunized with leukemia-derived EVs rich in CD80 and CD86 demonstrated dramatically better survival when exposed to L1210 cells than when the mice were immunized with unaltered leukemia-derived EVs." (PMID 37822925, 2023). "In our studies, neutrophils from TCL1 leukemia-bearing mice also revealed alterations, as we detected a significant decrease in the percentage of MHC-II- and CD80-expressing neutrophils." (PMID 37817276, 2023). "The LEXs highly expressing CD80 and CD86 were obtained from the supernatants of gene-transduced leukemia cells." (PMID 36466863, 2022). "Altogether, these data suggest that obtaining LEX highly expressing CD80 and CD86 through the costimulatory molecule gene-modified leukemia cells is feasible." (PMID 36466863, 2022). "LEX-CD8086 transfers its intrinsic LAA and molecules and acquired costimulatory CD80 and CD86 molecules to CD4+ T cells, making CD4+ TLEX-CD8086 cells both Th1 cells and APCs capable of inducing efficient leukemia antigen-specific CD8+ CTL response." (PMID 36466863, 2022). "In summary, our results indicate that modified LEXs overexpressing CD80 and CD86 can induce a more powerful immunity against leukemia cells." (PMID 32578140, 2020). "In this study, we constructed a novel LEX-based vaccine by combining CD4+ T cells with costimulatory molecules gene-modified LEXs, which harbor upregulated CD80 and CD86, and the anti-leukemia immunity of CD80 and CD86 gene-modified LEX-targeted CD4+ T cells was investigated." (PMID 36466863, 2022). "Genetically modification of leukemia cells to express costimulatory molecules such as CD80 has been successfully applied for almost all leukemia patient samples regardless of the type of leukemia." (PMID 35074008, 2022). "The majority of leukemia cells do not express CD80, only express low levels of CD86 and have poor T cell stimulatory capacity or even induce T cell anergy." (PMID 35074008, 2022). "The A20 leukemia transplantable cell line was chosen as the tumor model because PD-1 and PD-L2 cell surface receptors are completely absent and the expression of CD80 is barely detectable, whereas PD-L1 is clearly expressed." (PMID 35795681, 2022).
leukemia (continued). "CTLA-4/CD80/CD86—hampering T cell immunity against hematological malignancies and modulating immune responses in AML.Blocking of CTLA-4 pathway—increase of anti-leukemia T-cell immune response translated in prolonged tumor regression." (PMID 31649875, 2019). "In contrast, chronic lymphocytic leukemia has no or low levels of CD80/CD86 expression on leukemia cells with immunologic synapse formation defects and is resistant to pembrolizumab in a clinical trial." (PMID 29255458, 2017). "In addition, elevated levels of soluble CD80, and CD86 in some leukemia patients have been demonstrated, and elevated sCD86 levels have been reported as a marker of poor prognosis in acute myeloid leukemia." (PMID 23049754, 2012). "Moreover, upregulation of CD80 and CD86 expression in LEXs more effectively promoted DC maturation, CD4+ T cell proliferation, and Th1 cytokine secretion, thus inducing a stronger leukemia antigen-specific anti-leukemia CD8+ CTL response than LEX alone did." (PMID 36466863, 2022). "IFN-γ KO/KD also did not decrease the efficacy of anti-CD19 CAR Ts against leukemia/lymphoma models, while decreased the levels of some inflammatory cytokines (MCP-1, MIP-1β, IL-6, TNF-α, and IP-10) and macrophage activity markers (CD80 and CD86)." (PMID 41354926, 2025). "Although all mice immunized with LEX-CD8086 more obviously reduced tumor burden than LEX-null and PBS did, none showed long-term survival, suggesting that the upregulation of CD80 and CD86 expression alone in LEX-based vaccines may still not be sufficient to inhibit leukemia progression." (PMID 36466863, 2022).
atherosclerosis (29 papers, 2013 to 2026). A disease characterized by the build-up of fatty material and calcium deposition in the arterial wall resulting in partial or complete occlusion of the arterial lumen. "The depletion of Tregs, through combined Cd80/Cd86 genetic deficiencies in mice, aggravates atherosclerosis." (PMID 37681883, 2023). "However, a separate study found that Cd80/Cd86 deficiency reduced numbers of natural T regulatory (Treg) cells and led to increased atherosclerosis following 20 weeks of a high-fat, high-cholesterol diet." (PMID 37681883, 2023). "A combined genetic Cd80/Cd86 deficiency revealed a lowered atherosclerotic burden in early atherosclerosis, which may be attributed to a reduction in lesional APCs as well as a T helper (Th) 1 response." (PMID 37681883, 2023). "Notably, adoptive transfer of CD4+CD25+ Tregs abrogated the detrimental effects on atherosclerosis observed in Apoe−/− mice with the CD80/CD86–CD28 pathway deficiency." (PMID 34945203, 2021). "Mice deficient in CD80 and CD86 display reduced atherosclerosis and lower IFN-γ production by effector T cells, indicating that CD28-CD80/86 interactions prime T cells in atherosclerosis." (PMID 39817455, 2025). "Arginase 1 (ARG1), ATM, and CD80 are elevated with various forms of cardiovascular disease including the following: vascular dysfunction, coronary artery disease, and atherosclerosis in obese individuals." (PMID 36437471, 2022). "The immunological checkpoint proteins CD80/86-CD28/CTLA4 are essential regulators of atherosclerosis that either promote or suppress plaque inflammation." (PMID 36703734, 2022). "All these data show that CTLA4 inhibited plaque development by generating anti-inflammatory T cell responses, whereas CD80/86-CD28 co-stimulation promoted atherosclerosis by eliciting Th1 responses." (PMID 36703734, 2022). "In contrast, another study using irradiated BM chimeric mice of CD80/CD86 found a twofold increase in atherosclerosis accompanied by a decrease in Tregs." (PMID 33572939, 2021). "We investigated in this preclinical proof-of-concept study the applicability of the CD80/CD86-binding fusion protein belatacept as a probe for atherosclerosis imaging." (PMID 26728358, 2016). "In the present proof-of-concept study, we evaluated the potential of CD80/CD86-specific belatacept for atherosclerosis imaging." (PMID 26728358, 2016). "Due to the fact that deficiencies in the co-stimulatory molecules CD80 and CD86 have been shown to reduce atherosclerosis in mice, the surface expression of CD80 molecule on HUVECs was evaluated in the present study by assessing the MFI." (PMID 26622474, 2015). "A recent study has shown that CD28 influence the atherosclerosis development by co-stimulating T-cell with CD80/86." (PMID 24079748, 2013). "In addition, the abatacept-mediated inhibition of CD80/CD86-CD28 interactions reduced atherosclerosis in ApoE3*Leiden mice by preventing the activation of CD4+ T cells." (PMID 32872393, 2020). "Decreased expression of CD80 has been found to result in the inactivation of T cells, while decreased expression of ICAM-1 results in a reduction in leukocyte rolling; both are associated with the progression of atherosclerosis." (PMID 26622474, 2015). "We also identify key regulatory axes, such as CD47/Sirpa and Selplg/Vsir in AAA, and CD48/CD2, CD86/CD80, and CTLA-4/PD-1 in atherosclerosis, as potential therapeutic targets." (PMID 41216502, 2026). "The CD80/86-CD28 and CD80/86–CTLA-4 immune checkpoints regulate plaque inflammation in atherosclerosis." (PMID 39817455, 2025).
atherosclerosis (continued). "A study showed that CD80 and CD86 controlled the growth of atherosclerosis lesions and the activation of T cells that recognize lesional antigens." (PMID 36703734, 2022). "What’s more, APC-like neutrophils foster T cell response via HLA-DR, CD80 and CD86 in vitro, implying an immunostimulatory effect of APC-like neutrophils in atherosclerosis." (PMID 35251050, 2022). "Our recent study demonstrated that overexpression of CTLA-4 in T cells inhibited atherosclerosis development in Apoe−/− mice by downregulating the CD80 and CD86 expression on DCs and limiting the CD80/CD86–CD28-dependent activation of Teffs." (PMID 34945203, 2021). "Our observations are in line with previous studies that explored the role of the CD80/86-CD28 and -CTLA4 pathways in atherosclerosis." (PMID 32872393, 2020). "It is possible that downregulated expression of CD80, CD83, and CD88 by Dx can affect pathogenesis of atherosclerosis." (PMID 27340507, 2016). "111In-DOTA-belatacept accumulates in CD80/CD86-positive tissues in vivo and in vitro rendering it a research tool for the assessment of inflammatory activity in atherosclerosis and possibly other diseases." (PMID 26728358, 2016). "In aged Apoe-/- mice, inhibition of NOX4 activity using GKT137831 significantly reduced macrophage mitochondrial ROS and improved mitochondrial function, resulting in decreased CD68+CD80+ and increased CD163+CD206+ lesion macrophage proportion and attenuated atherosclerosis." (PMID 38975335, 2024). "Macrophages express CD80, CD86 and CD28 in human atherosclerosis lesions." (PMID 36703734, 2022). "Atherosclerosis was ameliorated and the production of IFN-c in the lymph nodes and spleen was reduced by their effector T cells in both CD80 and CD86-deficient hyperlipidemic animals." (PMID 36703734, 2022). "The role of CD80 and CD86 expression on B cells in atherosclerosis is less clear." (PMID 33572939, 2021). "In CD80–/–CD86–/–mice, the progression of atherosclerosis was delayed." (PMID 33613306, 2021). "CD80 and CD86 expressed by activated APCs are promising imaging targets in atherosclerosis." (PMID 26728358, 2016). "Since activated APCs that express CD80 and CD86 are a primary component of atherosclerotic lesions and the amount of APCs correlates with plaque vulnerability, CD80 and CD86 may be promising imaging targets in atherosclerosis." (PMID 26728358, 2016). "Tregs limit the CD80/CD86–CD28-dependent activation of T cells through CTLA-4-dependent downregulation of CD80 and CD86 expression on DCs, which may contribute to the reduction in atherosclerosis." (PMID 40608058, 2025).